CGAS (cyclic GMP-AMP synthase)
Diseases named in the same sentence as CGAS in open-access papers (continued):
Sharing a sentence is not in itself a finding about the gene and the disease.
tumor (continued). "In this study, we provided evidence that treatment with GPC3144‐152 peptide induced and enhanced effector/memory CD8+ T‐cell responses to TYST by activating the cGAS/STING signaling in tumor cells." (PMID 37986544, 2023). "This response was diminished when CD8+ T cells were depleted, and was shown to be dependent on paracrine DC activation from cGAS-STING signaling in tumor cells." (PMID 37627155, 2023). "Using a transgenic zebrafish line, we revealed that the presence of cGAS in tumor cells, at early stages, is sufficient to elicit myeloid cell recruitment and polarization into M1 macrophages that are key players in the initiation of antitumor responses." (PMID 36574362, 2023). "The PRR cGAS-STING was identified as a necessary upstream mediator in the type I IFN-dependent generation of endogenous antitumor immunity in immunogenic tumor types, identifying the downstream STING pathway as a critical bridge to activate cancer immunity." (PMID 37426669, 2023). "cGAS-STING pathway modulators have been studied intensively from the perspective of anti-tumor therapy." (PMID 37600809, 2023). "In contrast, pMMR/MSS exhibited low levels of tumor cell-intrinsic expression of cGAS-STING, resulting in reduced infiltration of CD8+ T cells." (PMID 37345163, 2023). "Through the induction of indoleamine 2,3-dioxygenase (IDO), the cGAS-STING pathway promotes tumor progression with low antigenicity." (PMID 36936940, 2023). "Together, the results indicate that tumor cell cytosolic detection of DNA by cGAS catalyzes the generation of 2′–5′ cyclic GMP‐AMP (cGAMP), which binds to STING, allowing it to recruit, phosphorylate, activate TBK1 and IRF3, and produce Type I IFNs." (PMID 37986544, 2023). "cGAS–STING signalling results in the production of type I interferons, which have been linked to immune cell infiltration in ‘hot’ tumours that are susceptible to immunosurveillance and immunotherapy approaches." (PMID 37534795, 2023). "The released Mn2+ is also involved in tumor immunotherapy through immune activation of the cGAS-STING pathway." (PMID 37153576, 2023). "In this model, loss of ENPP1 in the tumor inhibited metastasis and restored immune infiltration and sensitivity to treatment with immune checkpoint inhibitors, which required cGAS in the tumor cells and STING in the host cells." (PMID 37287967, 2023). "The nanovesicles can remold TAMs for reprogramming anti-cancer immunity and facilitating tumor eradication by inducing the cyclic GMP-AMP synthase/stimulator of interferon genes (cGAS/STING) pathway." (PMID 38022518, 2023). "The cyclic GMP-AMP synthase (cGAS)–STING pathway has emerged as an important intrinsic tumor-sensing mechanism." (PMID 38203256, 2023). "Enhanced type I IFN production, cGAS-STING signaling activation or the use of IR in combination with several other therapies can enhance anti-tumor immune responses." (PMID 36798129, 2023). "Although both cGAS and TLRs are expressed mainly by the innate immune cells, they are also expressed by the tumor cells." (PMID 36902456, 2023). "cGAS activators have rarely been tested in clinical settings; however, many targeted studies that attempt to overcome tumor immune resistance by activating cGAS are emerging." (PMID 37354378, 2023). "Altogether, we concluded that A3A increased the accumulation of cytosolic dsDNA by causing robust DNA damages, which subsequently activate cGAS-STING pathway and then potentiate anti-tumor immune signaling." (PMID 37215984, 2023). "Using antibodies that were validated on WT and CGAS-depleted cell pellets, we observed an inverse correlation between the frequency of cGAS+ micronuclei and tumour cell-intrinsic STING expression in human TNBC." (PMID 37612508, 2023). "The analysis of tumor samples before and after radiotherapy from 32 patients affected by CC reveals that increased expression of cGAS, ATF3, and PTGS2 as well as an high density of CD8+T-cells associate with a high disease-free survival rate." (PMID 37388241, 2023).
tumor (continued). "High linear energy transfer helium ion therapy and carbon ion radiotherapy induce a high level of immunogenic cell death proteins such as calreticulin, HSP‐70, DNA and others which stimulates the cGAS/STING pathway for radiogenic tumor death." (PMID 36411943, 2023). "The cGAS–STING pathway has mainly been examined through the lens of its tumour cell-extrinsic function: namely, the activation of cell-mediated immunity through type I IFN signalling." (PMID 36876871, 2023). "Antigen-presenting cells (APCs) can engulf tumor cells, and tumor-cell-derived DNA activates APCs through the cGAS-STING pathway." (PMID 37941028, 2023). "The frequency of mature DCs induced by tumor cells with different treatments was evaluated because of cGAS-STING activation." (PMID 37221157, 2023). "Targeting TRABID is a promising strategy for activating cGAS/STING-dependent anti-tumor immunity, thereby suppressing tumor growth and improving anti-cancer immunotherapy." (PMID 37237031, 2023). "While chronic activation of cGAS/STING signals can induce an immunosuppressive tumor microenvironment, a few studies have shown that cGAS/STING signals can promote tumor development and metastasis in certain circumstances." (PMID 37354378, 2023). "Tumor cells have developed intrinsic inhibitory mechanisms to prevent activation of the cGAS-STING axis, which enables them to evade immune surveillance." (PMID 37153627, 2023). "The potential for cGAS-STING to trigger innate immunity within the tumor microenvironment makes it a promising target for tumor therapy." (PMID 37153627, 2023). "STING, as an important regulator in tumor immunity, is one of the most hotly studied genes, and the cGAS-STING pathway constituted with GAS is an important DNA sensing mechanism in innate immunity and viral defense." (PMID 37055849, 2023). "How these discrepancies can be reconciled is unclear, but understanding in what contexts cGAS–STING produces pro-metastatic versus anti-tumour outcomes will be crucial to the appropriate administration of therapies that converge on STING pathway activation." (PMID 36876871, 2023). "The article further discusses utilizing MIC-specific cGAS/STING signaling modulation as critical tumor immunotherapy to alter TIME." (PMID 37380989, 2023). "When the cGAS-STING pathway in tumor cells is activated, cytokines such as IFN-I are induced, leading to apoptosis." (PMID 36769349, 2023). "We observed a poor infiltration of CD8+ and CD4+ T cells and an increased frequency of recurrence in pMMR/MSS CRC with the reduced expression or lost expression of cGAS-STING in tumor cells." (PMID 37345163, 2023). "The recruitment of cGAS-STING pathway plays an important role in tumor immunogenicity, and Its activation has been demonstrated to reduce mice’s resistance to PD-1 blockage." (PMID 36747120, 2023). "We further evaluated the effects of different treatments on the cGAS/STING pathway in 4T1 tumor-bearing mice." (PMID 37532731, 2023). "Considering the generation of more ROS and destruction of mitochondria in tumor cells, it will force the production of cytoplasmic dsDNA, thus activating cGAS-STING signaling pathway." (PMID 37061706, 2023). "In this study, we demonstrate that Gal-9 is induced by ATM inhibition through cGAS-STING-IFNβ pathway in a variety of tumor cells." (PMID 36778120, 2023). "Our results indicate that IDH3α overexpression leads to resistance to chemoimmunotherapy by regulating the acidic tumor microenvironments and the cGAS–STING pathway." (PMID 36980689, 2023). "Likely, this downregulation is either due to stimulated removal of DNA from the cytosol or downregulation of the cGAS-STING signaling pathway in the cancer cells within the tumor." (PMID 36882786, 2023). "Activated by micronuclei and chromosome bridges, cGAS-STING signalling promotes both tumour inflammation and progression." (PMID 38067140, 2023).
tumor (continued). "MnO2 nanomaterials have been widely used to play a role as biocompatible nano carriers, which can be combined with their cGAS-STING activation for more effective tumor treatment." (PMID 37153576, 2023). "The cGAS-STING pathway not only mediates the protective immune system against infection by various DNA-containing pathogens but also detects tumor-derived DNA, which activates intrinsic antitumor immunity." (PMID 37174127, 2023). "The correlation between DNA-damaging therapies and cGAS-STING pathway triggers more interest on combinatorial strategies to eliminate tumor cells through activation of immune responses." (PMID 37833461, 2023). "Functional cytoplasmic DNA sensing by the cGAS-STING pathway significantly contributes to tumor suppression on the organismal level." (PMID 38139802, 2023). "In this study, we examine the expression pattern of cGAS-STING in tumor cells and its effect on the infiltrations of CD8+ and CD4+ T cells, as well as clinical outcomes including survival and recurrence in patients with pMMR/MSS CRC." (PMID 37345163, 2023). "Recent studies have revealed that the cGAS-STING signaling pathway has a crucial role in tumor development and progression across cancer types." (PMID 37711192, 2023). "Given the significant potential of the cGAS-STING signalling pathway in anti-tumour therapy, the development of STING agonists has received considerable attention." (PMID 37448962, 2023). "Activation of cGAS-STING pathway further promotes the infiltration of lymphocytes in the tumor immune microenvironment to enhance anti-tumor immunity." (PMID 37920470, 2023). "Both radiotherapy and chemotherapy can facilitate the release of free DNA from damaged cells and instigate anti-tumor immunity through the activation of the cGAS-STING signaling pathway, an integral part of cancer treatment." (PMID 37920470, 2023). "Radiation therapy induces DNA damage in tumor cells, which promotes the release of dsDNA and activates the cGAS/STING pathway, leading to lymphocyte infiltration in tumor tissues." (PMID 37640735, 2023). "The upregulation of the cGAS-STING signaling pathway to augment the cytotoxic activity of lymphocytes presents a novel strategy for tumor immune checkpoint inhibitor therapy." (PMID 37920470, 2023). "Recent studies have shown that genomic instability in cancer benefits cancer immunotherapy, as it determines the immunogenicity of tumor cells through mechanisms including activating the cytosolic innate immunity mediated mainly by the cGAS-STING pathway." (PMID 37640708, 2023). "Here the authors show PRMT1 suppresses the anti-tumor immune response via arginine methylation of cGAS." (PMID 37193698, 2023). "This pathway is sufficient to activate tumor-intrinsic Type I IFN signaling in immunologically cold cancer models that lack an intact cGAS/STING signaling pathway, promote CD8+ T-cell-dependent anti-tumor immunity, and overcome anti-PD1 refractoriness in vivo." (PMID 36918588, 2023). "Upon stimulation with tumor-derived DNA, which activates the cGAS/STING pathway in DCs, the baseline and maximum glycolytic rates were increased and the maximum OXPHOS rates were decreased." (PMID 36821379, 2023). "Tumor cell-derived DNA accumulates in the cytoplasm of phagocytes, such as dendritic cells and macrophages, and triggers the activation of cGAS-STING signaling, thus facilitating antigen presentation and promoting acquired immune responses." (PMID 36861445, 2023). "The efficacy of ICI was substantially increased in tumor models when combined with cGAMP in a cGAS-STING signal-sufficient context." (PMID 37655095, 2023). "When treated with anti-tumor agents, cells experience DNA damage that triggers activation of the cGAS-STING pathway, culminating in the expression of type I IFNs and associated downstream interferon-stimulated genes." (PMID 37920470, 2023). "Clinically approved PARPis have been shown to induce IFN-I and CCL5 expression in tumor cells trough cGAS-STING." (PMID 36831435, 2023).
tumor (continued). "MnO2 nanomaterials can also regulate the anoxic tumor microenvironment, which can be combined with the activation of cGAS-STING pathway for more effective anti-tumor treatment." (PMID 37153576, 2023). "Persistent DNA damage caused by defective breast cancer gene (BRCA) pathway (disrupted BRCA1-PALB2 interaction) induces tumor immunosuppression through the cGAS-STING pathway, while also promoting T-lymphocyte infiltration." (PMID 37354378, 2023). "LID plus ultrasound enhance the nuclear delivery of doxorubicin, induce tumor mitochondrial DNA oxidation, and promote oxidized tumor mitochondrial DNA transfer to APCs for effective activation of cGAS-STING signaling." (PMID 37391428, 2023). "Release of IFN‐1 as a consequence of cGAS/STING activation is the main driver of the antitumor immune signaling induced by IR and enhances the attraction of DCs which process the tumor-associated antigens." (PMID 37420037, 2023). "Chronic activation of the cGAS-STING pathway can promote tumor formation and metastasis by inducing inflammation." (PMID 37920470, 2023). "DNA produced by tumor cells after radiotherapy promotes the anti-tumor effect of radiotherapy by triggering the cGAS/STING pathway to enhance T cell responses in mice to induce anticancer immunity in a STINE-dependent manner." (PMID 37667279, 2023). "For instance, increased CIN, as is caused by MCAK inhibition, has been shown to trigger IL-6 signaling through cGAS-STING to increase tumor cell survival." (PMID 37444419, 2023). "Conversely, studies have also demonstrated that cGAS/STING signaling can promote tumor expression and metastasis under certain circumstances." (PMID 37354378, 2023). "This review summarizes current research on the mechanisms underlying CDSs, absent in melanoma 2 (AIM2), cyclic GMP-AMP synthase (cGAS), and stimulator of interferon genes (STING)—downstream signaling effectors of cGAS—in the tumor microenvironment." (PMID 37046775, 2023). "The tumor-promoting effect of this CAF was remarkably weakened after the use of an inhibitor of STING or cGAS to suppress this pathway." (PMID 37784082, 2023). "While there is some evidence that cGAMP derived from tumor cells can diffuse into neighboring host immune cells, thus overcoming tumor cell STING deficiency in some models, cancer cell intrinsic cGAS expression remains important for cGAMP formation." (PMID 37079538, 2023). "In this work, we explore the synergy of immunity enhancement between gas therapy and Mn2+-based cGAS-STING promotion in both tumor cells and DCs." (PMID 37221157, 2023). "In this review, we highlight the latest understanding of the cGAS-STING pathway in tumor development and the advances in combination therapy of STING agonists and immunotherapy." (PMID 37153627, 2023). "Our study therefore defines the PRMT1/cGAS/PD-L1 regulatory axis as a critical factor in determining immune surveillance efficacy, which serves as a promising therapeutic target for boosting tumor immunity." (PMID 37193698, 2023). "In vitro studies of PARP inhibitors show a significant anti-tumour response dependent on BRCA1/2 deficiency, activation of the cGAS/STING pathway and recruitment of CD8+ T cells." (PMID 36831687, 2023). "Keywords co-occurrence and co-citation cluster analysis revealed that inflammation, senescence, and tumor were popular terms related to the cGAS-STING pathway recently." (PMID 35720348, 2022). "Activation of the cGAS-STING immune sensing pathway is a validated strategy to increase tumor immunogenicity and improve antitumor efficacy in preclinical and clinical studies." (PMID 36497445, 2022). "Meanwhile, we also observed that the reduction of cGAS expression reversed SENP3–9A-mediated inhibition of tumor growth in C57BL/6 mice." (PMID 35869062, 2022).
tumor (continued). "Radiation promotes the infiltration of CD8+ T cells into tumors by inducing DSBs to activate the cGAS/STING pathway and potentiates the antitumor immune response by releasing immunogenic tumor-associated antigens and chemokines." (PMID 36443299, 2022). "Activation of the cGAS-STING pathway promotes the infiltration of CTLs into tumor tissue and upregulates the expression of PD-L1 on the surface of cancer cells." (PMID 36353640, 2022). "The cGAS-STING nanoagonist enhances the tumor-specific T cell-mediated immune response against poorly immunogenic solid tumors in vivo, offering a robust approach for immunotherapy in the clinics." (PMID 36167857, 2022). "Nevertheless, the actual efficacy of several STING agonists in clinical trials was modest at most, revealing multiple key issues for cGAS-STING activation in tumor-encased DCs20." (PMID 36167857, 2022). "Immune tumor response is due to the endogenous secretion of interferon (IFN) β which activates tumor-infiltrating dendric cells following cellular DNA recognition (by dendritic cells) via the cGAS-STING pathway." (PMID 36010838, 2022). "Self-DNA released from tumor cells treated with cancer therapy activates the cGAS pathway in antigen-presenting cells such as dendritic cells, leading to the activation of antitumor immunity." (PMID 35563740, 2022). "Together these studies highlight the novel finding of the cGAS-STING pathway in stimulating tumor progression instead of suppression." (PMID 35992877, 2022). "Inhibition of PCAT1/SOX2 in collaboration with radiation further inhibited tumour growth, and initiated the cGAS/STING signalling pathway, which enhanced the immune responses of radiotherapy in NSCLC." (PMID 35415876, 2022). "It has been reported that cytoplasmic cGAS activates innate immune signaling in response to DNA damage or genome instability in tumor cells and thereby promotes the activation of CD8+ T cells and the efficacy of immune checkpoint blockades therapies." (PMID 36217001, 2022). "Others showed that STING/cGAS expression was lost in tumor tissues; however many of these studies involve only a small number of cases." (PMID 35099823, 2022). "Tumor cell-derived MPs (TMPs) can act as a cell-free tumor vaccine and stimulate dendritic cells via cGAS/STING signaling." (PMID 36275698, 2022). "PD-L1 signals intrinsic to tumor cells regulate the response following DNA damage, suppressing the accumulation of mutations and/or cGAS-STING detection, both of which affect tumor immunogenicity." (PMID 36376979, 2022). "In the current study, treatment by the combination of RU.521 and EGFR inhibitors (afatinib or gefitinib) on two independent PDTOs supports the tumor-suppressing activity of co-inhibition of the cGAS-STING and EGFR pathways." (PMID 35992877, 2022). "Currently several pre-clinical models in mice have shown promising results utilizing various cGAS/STING agonists to enhance tumor clearance." (PMID 36059473, 2022). "The cyclic GMP-AMP synthase-stimulator of the interferon genes (cGAS-STING) pathway is essential in inflammation-driven tumor occurrence and progression." (PMID 36550819, 2022). "Deciphering the tumor immune microenvironment reprogrammed by the cGAS-STING pathway is of great importance to understand cancer development in each cancer type." (PMID 35983076, 2022). "Taken together, cGAS-STING activation in the tumor microenvironment is important for anti-tumor activity and its regression." (PMID 36139387, 2022). "Published results show that different cancers upregulate cGAS/STING pathway, likely causing chronic inflammation leading to the survival of tumour cells, cancer progression and high resistance towards cytotoxic agents." (PMID 35794238, 2022). "Activation of an IFN-I response via the cGAS/STING pathway in tumor cells has been shown to be critical for the effects of RT in stimulating an in situ vaccine effect and potentiating response to ICBs32,33." (PMID 35999216, 2022).